EGFR (epidermal growth factor receptor)
Diseases named in the same sentence as EGFR in open-access papers (continued):
Sharing a sentence is not in itself a finding about the gene and the disease.
tumor (continued). "Tumor-bearing mice were imaged with [18F]FSPG PET before and one week following the initiation of treatment with either EGFR-targeted monoclonal antibody (mAb) therapy, glutaminase inhibitor therapy, or the combination." (PMID 36961000, 2023). "This means that the tumor cells produce TGF-α, which binds to EGFR on the same cells, stimulating their growth." (PMID 38202116, 2023). "Tyrosine kinase inhibitors—inhibition of EGFR and ERBB2/HER2 signaling pathways lead to tumor cell death, inhibition of cell growth, angiogenesis, and metastasis." (PMID 37039257, 2023). "By activating the EGFR/PI3K/AKT pathway, its upregulation leads to tumor growth and metastasis in HCC22." (PMID 38114725, 2023). "This proactive detection, made possible through initial follow-up images after starting EGFR-TKI treatment, offers insights into the tumor’s response, be it regression, stabilization, or progression." (PMID 37958300, 2023). "PD-L2, IFN-γ, EGFR, VEGF, TGF–β, TMB, blood TMB, CD73, TILs, alternative splicing, tumor microenvironment, and some macroscopic and radiological features are promising predictors worthy of further studies." (PMID 36900006, 2023). "The EGFR L858R-derived NeoAg peptides cocktail vaccine was administered in patients with stage III/IV NSCLC and led to remarkable tumor regression and robust immune response." (PMID 37766136, 2023). "For example, the receptor tyrosine kinase EGFR interacts with the proapoptotic molecule PUMA in the cytoplasm, leading to tumor drug resistance." (PMID 37371581, 2023). "Because of the interplay of mechanisms, combining EGFR TKIs and VEGF inhibitors seems to be a rational approach to combat tumor resistance and increase the efficacy of anti-tumor therapy." (PMID 36865093, 2023). "Autophosphorylation of tyrosines in the intracellular domain of the epidermal growth factor receptor (EGFR) activates downstream tyrosine kinases and signaling pathways involved in tumor growth, survival, angiogenesis, invasion, and metastasis." (PMID 38248726, 2023). "We also unveiled that in addition to co-occurrence of gene amplification among CBX3, EGFR and RAC1, also low-grade CNVs of these genes strongly co-occur in several human tumor types and are much more recurrent than high-grade CNVs." (PMID 37633946, 2023). "EPB41 suppresses epidermal growth factor receptor (EGFR) activation and thus plays an important role as a tumor suppressor in cancer development." (PMID 37444464, 2023). "This family comprises the epidermal growth factor receptor (EGFR) and the fibroblast growth factor receptor (FGFR), which crosstalk with major tumour-promoting signalling pathways." (PMID 37686122, 2023). "A twelve peptide named GE 11 (YHWYGYTPQNVI) can effectively bind EGFR and release DOX to kill tumor cells." (PMID 37691919, 2023). "Lastly, IHC results of tumor tissues corroborated the relative protein expression levels of LAMC2 and EGFR in the three experimental groups in that LAMC2 and EGFR protein levels were highest in the NC group and lowest in the LAMC2 KD group." (PMID 37542131, 2023). "In this study, the galectin-3-mediated tumour cell-cell homotypic aggregation and promotion of EGF-induced EGFR activation are seen to be significantly reduced following C1GalT1-suppression." (PMID 37612278, 2023). "EGFR-TKI can block signal transduction in tumor cells by competitively inhibiting TK phosphorylation, tumor growth, and metastasis." (PMID 36890493, 2023). "The immunogenicity of a cetuximab-treated mouse CRC cell line (CT26) expressing human EGFR (hEGFR-CT26) increased and the tumor cells induced an effective anti-tumor response." (PMID 37153795, 2023). "Preclinical models seem to suggest that drugs targeting VEGF, FGFR, epidermal growth factor receptor (EGFR), and other signaling pathways can improve the tumor microenvironment and reshape the immune response to inhibit tumor progression." (PMID 38162488, 2023).
tumor (continued). "We characterize the affinity of the bispecific Nanofitin for each target and its ability to target EGFR and PDL1-positive tumor cells selectively." (PMID 37189383, 2023). "When TNBC cells are chronically exposed to Lapatinib or other TKIs targeting EGFR, this is accompanied by ANXA6 upregulation and LE/Lys-Chol accumulation, ultimately leading to tumor resistance." (PMID 37129645, 2023). "Epidermal growth factor receptor (EGFR) is a driver of tumorigenesis; after phosphorylation, EGFR promotes tumor development by activating proto-oncogenes." (PMID 37998363, 2023). "In mice, the systemic delivery of STAT3/EKEVs suppressed tumor xenografts via STAT3-induced apoptosis, combating the EGFR resistance." (PMID 37754880, 2023). "The epidermal growth factor receptor (EGFR) and human epidermal growth factor receptor 2 (HER2), the preferred heterodimer partner of EGFR, are cell surface receptor tyrosine kinases (RTK), and their activation promotes tumor cell proliferation." (PMID 37798461, 2023). "Affinity extraction showed that in the xenograft tumor, Oncotag interacts only with α7-nAChR, while SLURP-1 also binds EGFR." (PMID 37854069, 2023). "The PDAC‐related markers CA19‐9, CEA, EGFR, Ki67, and HER2 in the organoid tissues were consistent with those of patient tumor tissues, suggesting that these two PDO models better maintained the clinical characteristics of primary tumors." (PMID 37890865, 2023). "Common prognostic indicators of glioblastoma include Karnofsky performance status (KPS), age, extent of tumor resection, radiotherapy, chemotherapy, tumor size, tumor location, and molecular profiling for biomarkers such as IDH1, EGFR, PTEN, and MGMT." (PMID 37899778, 2023). "Furthermore, targeting transforming growth factor (TGF)-β, either through inhibition or suppression, could potentially be an effective way to reduce cancer progression and increase the effectiveness of existing anti-tumor therapies such as epidermal growth factor receptor (EGFR)-targeted therapy." (PMID 37160480, 2023). "In the epidermal growth factor (EGF)/epidermal growth factor receptor (EGFR) signal transduction pathway related to tumor invasion, GLUT1 is positively correlated with the expression of the EGFR HER-2 and tumor vascular EGF." (PMID 37542344, 2023). "We suggest that the presence of IL-17A within the tumor microenvironment of NSCLC probably promotes and sustains EGFR activation and ultimately results in tumor proliferation." (PMID 37444399, 2023). "SNS-032 was able to induce the degradation of SIX1 through the inactivation of the EGFR-AKT-USP1 axis, and SNS-032 in combination with sorafenib was found to inhibit tumor growth in a mouse model of HCC." (PMID 36750914, 2023). "Heterodimer formation between EGFR and HER2 favours the recruitment of a greater number of intracellular signals involved in growth, survival and metastasising capacity of tumour cells." (PMID 38414930, 2023). "When the dominant pathway, such as EGFR, is inhibited by a TKI, tumor cells tend to turn on the critical downstream effector through bypass signaling pathways, maintaining continued cell survival and growth." (PMID 37301856, 2023). "Analyses were focused on identifying which biological pathway activations were associated with image features that were shown to correlate with survival benefit from EGFR TKI therapy, specifically, tumor-tumor and tumor-stroma interactions." (PMID 36647832, 2023). "The epidermal growth factor receptor (EGFR) family, also called the erbB protein family, plays a major role in tumor cell proliferation and tumor vascularization." (PMID 36903565, 2023). "Immunotherapy is considered the standard approach for most patients with newly diagnosed EGFR-WT/ALK-WT mNSCLC and tumour PD-L1 ≥ 50%." (PMID 37386452, 2023).
tumor (continued). "Several clinical trials are also currently underway to evaluate the anti-tumor efficacy of CAR T-cells producing antibodies against CTLA-4 and PD-1 in MUC1+, EGFR+, and mesothelin+ solid tumors (NCT03179007, NCT03182816, and NCT03182803)." (PMID 37020537, 2023). "There were two salient findings in this study: first, that PAI could reliably detect tumor presence in fresh tissue samples with signal alone; and second, that imaging debulked margin tissue compared to the main specimen improved correspondence with EGFR IHC staining." (PMID 37427140, 2023). "The anti-EGFR-genistein ADC demonstrated good tolerability up to 140 mg/kg, and significant anti-tumor activity at 1 mg/kg in preclinical models." (PMID 36650546, 2023). "Unfortunately, acquired resistance still develops in patients after EGFR‐TKI treatment, leading to tumor recurrence and metastasis." (PMID 36594109, 2023). "Our results indicate that AV25R binds with several proteins known to regulate cell proliferation and tumor progression, such as FECH, MAP11, EGFR, TGFBR1 and MDM2." (PMID 38138609, 2023). "Treatment with BTK (MCL) and EGFR (NSCLC) inhibitors increased target ligand, conditionally driving CER-1236 function to augment anti-tumor responses." (PMID 37194236, 2023). "KEYNOTE-055 support the safety, tolerability and anti-tumour activity of pembrolizumab as a monotherapy in patients with HNSCC with disease progression on platinum-based and cetuximab (EGFR mAb) therapy." (PMID 36980527, 2023). "The combination of Western and Chinese medicine using EGFR-TKI and ZLJT represents a promising tumor treatment strategy." (PMID 37990309, 2023). "Compared with the control group, the expression levels of tumor metastasis-related genes EGF and EGFR were significantly increased in the MYL1 overexpression group." (PMID 37679666, 2023). "Compared with UA alone, USMNS-Cl significantly downregulated the expression of epidermal growth factor receptor (EGFR) and vascular endothelial growth factor receptor 2 (VEGFR2) and inhibited tumor angiogenesis in vitro and in vivo." (PMID 36945005, 2023). "In vivo, EGFR inhibitors combined with FGFR inhibitors have been demonstrated to block DTC expansion and restrain their long‐term survival, thus preventing tumor recurrence." (PMID 37638338, 2023). "3DCRT combined with SBRT is effective and safer in patients with EGFR-mutant oligometastatic NSCLC, and significantly improves the patient's immune and tumor marker levels." (PMID 36846051, 2023). "Preclinical studies using various agents targeting EGFR, such as gefitinib, lapatinib and anti-EGFR monoclonal antibodies (cetuximab or mimotuzumab), have shown significant antitumor activity against WSCC tumor cell overexpression in EGFR." (PMID 36661697, 2023). "The present study showed that EGFR was expressed relatively higher while HER4 was lower, in both HER2 positive and TNBC tumours." (PMID 37333824, 2023). "In the relation of risk score with oncogenic pathways, EGFR, hypoxia, PI3K, and VEGF pathways were positively correlated with risk score (R = 0.42, 0.42, 0.36, and 0.28, respectively), suggesting that these pathways may be highly involved in the TME modulation and tumor progression." (PMID 36726580, 2023). "Down-regulation of survivin reverses EGFR TKI resistance in T790M mutant NSCLC cells and sensitizes the tumor to erlotinib." (PMID 36865093, 2023). "In patients with a right-sided tumor and wild-type RAS, median OS was 18.62, 19.31, and 24.62 months with anti-VEGF, anti-EGFR, and chemotherapy alone, respectively (p = 0.201)." (PMID 37760572, 2023). "This study revealed that the circEMB/miR-3184-5p/EGFR axis regulates the progression of OSA by regulating cell proliferation, tumour invasion and metastasis, apoptosis and cell cycle arrest." (PMID 36611218, 2023). "Nevertheless, FST represents a novel modulator of the complex EGFR–TGF-β–p63 axis and the tumor microenvironment in HNSCC." (PMID 37492374, 2023).
tumor (continued). "At the single-cell level, tumor cells expressed low levels of CHST11 compared with ALDH3B1, EGFR, ERAP2, MSLN, and NCEH1." (PMID 37251940, 2023). "Independently of the tumour–node–metastasis (TNM) stage, the majority of laboratories (79.2%, 42/53) indicated carrying out ‘reflex’ EGFR testing." (PMID 37713929, 2023). "Clinicopathological analysis supported these findings by revealing a positive correlation between the expression of IL-1RA and phosphorylated EGFR and JNK in OSCC tumor tissues." (PMID 37461111, 2023). "As expected, we also detected lower protein levels of EGFR and TNS4 in tumor tissues of SMARCA4-R1157W mutant CDX models after treatment with GSK-PTi and BBAi-1 by western blot and IHC analysis than those in SMARCA4-WT CDX models." (PMID 36922568, 2023). "C-Met interacts with other oncogenic molecules (such as EGFR and RON) to activate downstream pathways, thereby mediating tumor progression and drug resistance." (PMID 36959792, 2023). "As for EGFR-targeted antibodies, cetuximab proved to have ADCC activity against tumor cells, which was dose-dependent on cell surface EGFR expression." (PMID 38201251, 2023). "In the same study, analysis of circulating tumor DNA (ctDNA) revealed the progressive onset of MYC, EGFR, FGFR2, and MET amplifications in the progression phase of the disease." (PMID 35834132, 2023). "The anti-tumor activity of erlonitib+MLN0128 was synergistic and produced inhibition of the p-EGFR, mitogen-activated protein kinase (MAPK), and Phosphoinositide 3-kinase (PI3K) pathways in culture." (PMID 36831214, 2023). "We identify differently cfChIP enriched genes including EGFR, CRMP1 and SMAD4 with known differential gene expression between the two tumour types that we verify using RNA‐seq data from NSCLC and SCLC cell lines." (PMID 36825535, 2023). "Once CD27xEGFR binds to EGFR+ cancer cells, the CD27-targeting domain can provide multivalent and tumor-localized crosslinking of CD27, potentially reducing off-tumor side effects." (PMID 37545491, 2023). "In comparison with traditional EGFR CAR-T cells, live imaging indicated that EGFR CAR-E27-CCR6 T cells displayed superior anti-tumor function." (PMID 36982500, 2023). "We detected a better pathological response of the primary tumor (p = 0.005) and a better RFS (p = 0.047, log-rank) with the VEGF compared to the EGFR antibody therapy." (PMID 37296862, 2023). "Decreased FUT1 is correlated with low EGFR-TKI responsiveness, poor prognosis and tumor metastasis of NSCLC." (PMID 37256139, 2023). "The third-generation EGFR TKI AZD9291, which can overcome T790M-mediated TKI resistance, significantly suppressed the tumor growth in H1975 xenografts, but had a weak effect on A549 xenograft tumors." (PMID 37813845, 2023). "Among the top ten MRs identified by MARINa, only two genes (EGFR and NCAM1) have abnormal copy number for at least 30% of tumor samples." (PMID 37894336, 2023). "In vivo, OV-IL15C and EGFR-CAR NK-cell therapy demonstrated a synergistic effect, reducing tumor burden post-treatment on day 15, prolonging survival, and generating 25% of long-term surviving mice (>50 days) in a GBM30 PDX mouse model." (PMID 38136398, 2023). "Both EGFR and MT4-MMP have been shown to cooperate in tumor cell invasion and signaling, driving cancer cell growth through the regulation of cell cycle proteins such as CDK4 activation and retinoblastoma protein inactivation." (PMID 37373092, 2023).
tumor (continued). "CIC inactivation by mutations or deletion increases the level of histone acetylation, leading to transcription of EGFR/RAS/MAPK pathway components, promoting mitogen-independent tumor growth." (PMID 37185778, 2023). "Altogether, SRC activation induces a tumor survival mechanism that acts in parallel to both the MAPK and EGFR signaling axes in BRAFV600E CRC." (PMID 36759733, 2023). "Our results also validate that CA3, in combination with osimertinib, executes its anti-metastasis and pro-tumor apoptosis partly through autophagy and the YAP1/DUSP1/EGFR/MEK/ERK regulatory feedback loop in osimertinib-resistant cells." (PMID 37215986, 2023). "Calcitriol down-regulates the action of the epidermal growth factor receptor (EGFR) and activates its ligand-induced internalisation in tumour cells." (PMID 37299554, 2023). "A previous study with linsitinib, crizotinib, and gefitinib that target IGFR1, MET, and EGFR decrease mRNA MYB-NFIB levels or even block protein synthesis, which promote cell differentiation and decrease of tumor growth in vivo and in vitro." (PMID 37476370, 2023). "Moreover, limited stability and early release of labelled iodine from their conjugated VHH before reaching their target protein might limit clinical usefulness, as was shown for the application of 125I-labelled EGF in an in vivo model of an EGFR overexpressing tumor." (PMID 37746282, 2023). "The author argues that ERβ (especially ERβ1) exerts cancer-suppressive effects, such as oppressing the proliferative effects of ERα, inhibiting epidermal growth factor receptor (EGFR) and suppressing tumor bone metastasis." (PMID 37361598, 2023). "Prostaglandins (PG) can upregulate the expression of EGFR in family patients with multiple adenomas, while aspirin can reduce PG synthesis by inhibiting the synthesis of COX-2 in tumor cells." (PMID 37564983, 2023). "Gefitinib, a tyrosine kinase inhibitor targeting EGFR, attenuated POMC expression and ACTH secretion in human and canine corticotroph tumor cell cultures." (PMID 36672445, 2023). "HIF activation promotes tumorigenesis by inducing a metabolic shift to glycolysis, promoting the transcription of genes such as vascular endothelial growth factor (VEGF), and a tumor-promoting mechanism between HIF and EGFR." (PMID 37601653, 2023). "Preclinical studies have shown that concomitant inhibition of pathways involving EGFR and VEGF/VEGFR can produce biological synergies against tumor activity." (PMID 36997925, 2023). "Regarding stage II–III nonsquamous NSCLC patients receiving surgery and platinum-based adjuvant chemotherapy, it was found that EGFR alteration was an independent predictor for shorter relapse-free survival (RFS) and tumour recurrence." (PMID 37760531, 2023). "The combination therapy of neratinib (an EGFR/ERBB2 inhibitor) and cobiotinib (a MEK inhibitor) exhibited synergistic anti-tumor proliferation exclusively in organoids derived from patients with high KDS30 mt KRAS rather than low ones." (PMID 37941550, 2023). "The optimal compound 9j exhibited excellent activity for both EGFR T790M/L858R, EML4-ALK kinases, and inhibition activity against tumor cell proliferation." (PMID 36903251, 2023). "Again, this observation matchedwith the essential role of oncogene phosphorylation to induce tumor progression; examples include the phosphorylation of BRD4, Smad3, and EGFR." (PMID 37106813, 2023). "Reports have shown that JNK/c-Jun signaling induces activation of EGFR signaling via HB-EGF overexpression in various types of cancer, promoting tumor invasion and drug resistance." (PMID 36702855, 2023). "Overall, the daily combination of savolitinib 600 mg and gefitinib 250 mg showed acceptable safety profiles and promising anti-tumor activity in patients with advanced EGFRm and MET amplification NSCLC who had received previous EGFR-TKI treatment." (PMID 37835402, 2023).